SALL4 (spalt like transcription factor 4)
Description:
Transcription factor with a key role in the maintenance and self-renewal of embryonic and hematopoietic stem cells.
Synonyms: ZNF797; dJ1112F19.1; DRRS; HSAL4; IVIC
Tractability: Small molecule: a structure with a bound ligand is known; a high-quality ligand is known. PROTAC: UniProt records ubiquitination sites on it.
Gene: Protein-coding gene on chromosome 20 (51,782,331 to 51,802,521, reverse strand). Ensembl gene ENSG00000101115.
Subcellular location: Cytoplasm; Nucleus
Subcellular location (Human Protein Atlas): Nucleoplasm; Vesicles
Pathways (Reactome):
Developmental Biology: POU5F1 (OCT4), SOX2, NANOG activate genes related to proliferation; Transcriptional regulation of pluripotent stem cells
Signal Transduction: Regulation of PTEN gene transcription
Gene Ontology:
Molecular function: protein binding; DNA-binding transcription factor activity, RNA polymerase II-specific
Biological process: regulation of transcription by RNA polymerase II
Cellular component: nucleoplasm; nucleus; cytoplasm; heterochromatin; protein-containing complex
Genetic constraint (gnomAD): Loss-of-function variants: 6 observed, 64.48 expected, observed/expected ratio (o/e) 0.093, 90% interval 0.05 to 0.18. The upper end of that interval is the gene's LOEUF score, 0.18, which puts it in group 1 of 6, group 1 being the genes least tolerant of losing a copy. Missense variants: 1,178 observed, 1,461.7 expected, observed/expected ratio (o/e) 0.81, 90% interval 0.77 to 0.85. Synonymous variants: 580 observed, 604.37 expected, observed/expected ratio (o/e) 0.96, 90% interval 0.9 to 1.03.
Cancer hallmarks: change of cellular energetics; proliferative signalling (promotes); genome instability and mutations (suppresses); invasion and metastasis (promotes); angiogenesis (promotes); invasion and metastasis (suppresses); escaping programmed cell death (promotes); genome instability and mutations (promotes)
Homologues: Orthologues: chimpanzee SALL4 (99% identical), macaque SALL4 (98% identical), dog SALL4 (87% identical), pig SALL4 (85% identical), rabbit SALL4 (81% identical), rat Sall4 (76% identical), mouse Sall4 (75% identical), tropical clawed frog sall4 (51% identical), zebrafish sall4 (47% identical). Paralogues in human: SALL3 (45% identical), SALL1 (42% identical), SALL2 (24% identical), HIVEP3 (15% identical), HIVEP1 (15% identical), ZNF536 (14% identical), HIVEP2 (14% identical), BCL11B (12% identical), BCL11A (12% identical), ZNF516 (11% identical), ZNF831 (10% identical), ZNF219 (10% identical), and 2 more.
Diseases named in the same sentence as SALL4 in open-access papers:
SALL4 is named in the same sentence as 205 diseases in open-access papers, as found by Europe PMC text mining. Sharing a sentence is not in itself a finding about the gene and the disease. The quoted sentences say what the papers report.
gastric cancer (54 papers, 2011 to 2025). A primary or metastatic malignant neoplasm involving the stomach. "We have previously shown that SALL4 is highly expressed in gastric cancer and its upregulation is associated with lymph node metastasis and poor prognosis." (PMID 32489324, 2020). "Another study proposed that SALL4 tissue expression was associated with older age, male sex, intestinal-type histology, and synchronous hepatic metastasis in gastric carcinoma." (PMID 24860834, 2014). "In addition, the HDAC inhibitor entinostat partially targets SALL4 and suppresses the proliferation, migration, and invasion of gastric cancer cells by regulating the expression of EMT-associated proteins." (PMID 38584262, 2024). "AFP is closely associated with SALL4 expression in gastric carcinoma (both, P<0.0001)." (PMID 38817451, 2024). "Moreover, the association between high SALL4 expression and poor patient survival is also proved in lung cancer, gastric cancer, endometrial cancer, and myelodysplastic syndrome." (PMID 29691367, 2018). "To demonstrate whether SALL4 knockdown affects the expression of both standard and variant isoforms of CD44, we examined the expression of CD44s and CD44v6, a CD44 variant that is closely related to gastric cancer, in SALL4 knockdown gastric cancer cells." (PMID 27819668, 2016). "Besides, they also found that the expression level of SALL4 was associated with EMT in gastric cancer cells." (PMID 26317546, 2015). "SALL4 is also overexpressed in gastric cancer and is linked with the EMT as well as stemness." (PMID 25919570, 2015). "Supporting this, prior studies have shown co-expression of YAP1 and SALL4 in gastric cancer stem cells, suggesting a cooperative role in lineage commitment during tumorigenesis." (PMID 40932240, 2025). "SALL4 drives gastric cancer progression by regulating hexokinase II (HK2), further highlighting the role of glycolytic enzymes in tumor metabolism." (PMID 41220952, 2025). "Based on these findings, SALL4 is the only potential target gene of miR-497 in gastric cancer, as has been revealed in HCC cells." (PMID 38584262, 2024). "In gastric cancer, intraperitoneal seeding is accompanied by enhanced glycolysis mediated by stem cell factor SALL4, which transcriptionally activates HK2 expression." (PMID 38643448, 2024). "SALL4 is excessively expressed in various malignant tumors, such as esophageal cancer, gastric cancer, colorectal cancer, hepatocellular carcinoma (HCC), breast cancer, lung cancer and acute myeloid leukemia (AML)." (PMID 38584262, 2024). "KDM6A is upregulated in gastric cancer and can regulate the expression of SALL4, thereby promoting the growth and metastasis of gastric cancer." (PMID 38840262, 2024). "In gastric cancer, PGE2 maintains the expression of stem cell-associated proteins (OCT4, CD44, and SALL4) and promotes inflammatory microenvironment formation." (PMID 38704736, 2024). "The effects of conditioned medium (CM) from SALL4 knockdown or overexpression of gastric cancer cells on endothelial cell proliferation, migration, and tube formation were investigated by CCK-8 assay, transwell migration assay, and tube formation assay." (PMID 37525212, 2023). "In this study, we investigated the biological roles and mechanisms of SALL4 in the pathogenesis of gastric cancer." (PMID 37525212, 2023). "Taken together, these in vitro observations validate the potent role of SALL4 in gastric cancer angiogenesis." (PMID 37525212, 2023). "To further verify the effect of SALL4 expression on gastric cancer angiogenesis, we first established a gastric cancer cell line with SALL4 knockout by using CRISPR/Cas9 technology (MGC-803-SALL4 KO)." (PMID 37525212, 2023). "A probable function interaction between the spalt-like transcription factor 4 (SALL4) and linc-ROR was associated with tumor maintenance and aggressiveness in gastric cancer (GC) tissues with helicobacter pylori infection." (PMID 36827545, 2023).
gastric cancer (continued). "More importantly, SALL4 bound to the promoter regions of VEGF family genes and initiated histone modifications to activate their expression, suggesting that SALL4 plays an important role in gastric cancer progression by regulating VEGF." (PMID 37525212, 2023). "Consistent with the binding of SALL4 to VEGF family gene promoters in the MGC-803 gastric cancer cells transfected with P-SALL4, H3–K79 di-methylation and H3–K4 trimethylation were detected and increased in these cells as compared with control vector group." (PMID 37525212, 2023). "Collectively, these results suggest that SALL4 has a vital role in gastric cancer angiogenesis through directly binding to VEGF gene promoters." (PMID 37525212, 2023). "Recent studies have shown that SALL4 plays an important role in many solid tumors, including in esophageal cancer, cervical cancer, and gastric cancer." (PMID 35692499, 2022). "Recently, SALL4 overexpression was found in malignant cancers, including lung cancer, hepatocellular carcinoma, breast cancer, gastric cancer, colorectal cancer, osteosarcoma, acute myeloid leukemia, ovarian cancer, and glioma." (PMID 35216168, 2022). "Recently, in addition to AFP, glypican-3 and SALL4 have been considered effective in diagnosing AFP-producing gastric cancer as fetal cancer proteins." (PMID 34792649, 2021). "Among the GC subtypes, SALL4 expression was negatively correlated with Epstein–Barr virus (EBV) infection (P < 0.001), which is also referred to as EBV associated gastric cancer (EBVaGC) and is generally acknowledged to have a favorable prognosis." (PMID 33644042, 2021). "The role of SALL4 in cell dispersion has been investigated using cell lines of breast cancer, endometrial cancer, and gastric cancer." (PMID 34441397, 2021). "The previous studies have shown that SALL4 overexpression promotes gastric cancer cell proliferation, migration, and invasion." (PMID 32489324, 2020). "To identify the downstream genes and signaling pathway regulated by SALL4, we have previously performed a microarray to compare the differentially expressed genes between control and SALL4 knockdown gastric cancer cells." (PMID 32489324, 2020). "SALL4 knockdown inhibited glucose uptake, lactate production, lactate dehydrogenase activity, ATP level and hexokinase activity in gastric cancer cells, and decreased the expression of glycolytic genes and proteins." (PMID 32489324, 2020). "The effects of SALL4 on glycolysis and gastric cancer progression in vivo were determined by subcutaneous xenograft and peritoneal metastasis tumor models in nude mice." (PMID 32489324, 2020). "Enforced expression of SALL4 not only enhances the proliferation and migration of human gastric cancer cells, but promotes the growth and metastasis of gastric xenograft tumor in vivo." (PMID 31992202, 2020). "We found that the proliferation, migration and invasion abilities of gastric cancer cells, which had been enhanced by SALL4 overexpression, were weakened after interfering with HK-2 expression." (PMID 32489324, 2020). "Then, we compared glucose uptake, lactate production, lactate dehydrogenase activity and ATP level in gastric cancer cells with SALL4 knockdown or overexpression." (PMID 32489324, 2020). "Increased levels of BMI-1 activated the stemness state in gastric cancer cells, induced by overexpression of SALL4." (PMID 32819319, 2020). "Taken together, these results suggest that SALL4 regulates the expression and activity of HK-2 in gastric cancer cells." (PMID 32489324, 2020). "In conclusion, our findings show that SALL4 induces glycolysis via the upregulation of HK-2, thus promoting the proliferation, migration and invasion of gastric cancer cells." (PMID 32489324, 2020). "HK-2 knockdown abrogated the promotion of glycolysis by SALL4 in gastric cancer cells, indicating that HK-2 acts as a downstream effector of SALL4." (PMID 32489324, 2020).
gastric cancer (continued). "We found that SALL4 promoted glycolysis by enhancing the expression of HK-2 and interfere with HK-2 expression inhibited the promoting role of SALL4 in gastric cancer cell proliferation, migration and invasion." (PMID 32489324, 2020). "In consistence with these findings, our results showed that SALL4, at least in part, promoted gastric cancer progression by regulating HK-2-mediated glycolysis." (PMID 32489324, 2020). "In the present study, we showed that SALL4 overexpression promoted while SALL4 knockdown inhibited glycolysis in gastric cancer cells." (PMID 32489324, 2020). "Our study not only reveals a new mechanism for the oncogenic roles of SALL4 in cancer, but also provides evidence for the potential of SALL4 as a therapeutic target for gastric cancer." (PMID 32489324, 2020). "SALL4 promotes gastric cancer progression through HK-2-mediated glycolysis, which reveals a new mechanism for the oncogenic roles of SALL4 in cancer." (PMID 32489324, 2020). "The relevance of these in vitro results to human gastric cancer is supported by the positive correlation between IL-17RB and OCT4, NANOG, LGR5, and SALL4 mRNA expression in human gastric cancer tissues." (PMID 32373132, 2020). "SALL4 promoted the glycolysis of gastric cancer cells by activating the expression of HK-2, a key rate-limiting enzyme of glycolysis." (PMID 32489324, 2020). "HK-2 knockdown reversed the promotion of gastric cancer cell proliferation, migration, and invasion by SALL4." (PMID 32489324, 2020). "Transwell migration assay, matrigel invasion assay, cell counting assay and colony formation assay were used to study the roles of HK-2 regulation by SALL4 in gastric cancer cells in vitro." (PMID 32489324, 2020). "Immunohistochemically, the adenocarcinomatous component with clear cytoplasm comprised areas with alpha-fetoprotein (AFP)- and Sal-like protein 4 (SALL4)-positive AFP-producing gastric carcinoma." (PMID 32972454, 2020). "In gastric cancer, SALL4 was reported to play oncogenic roles through the modulation of epithelial–mesenchymal transition (EMT) and cell stemness." (PMID 30989433, 2019). "We have previously shown that SALL4 is critically involved in gastric cancer progression by regulating cell stemness and EMT." (PMID 29416741, 2018). "Twenty-five gastric cancers that were diagnosed as AFP-producing gastric cancers, were examined for the expression of SALL4, LIN28A, and LIN28B by immunostaining." (PMID 29802314, 2018). "We found that AFP, LIN28B, and SALL4 were overexpressed in seven, eight, and nine cases of the 200 human gastric cancers, respectively." (PMID 29802314, 2018). "Consistently, human AFP-producing gastric cancers often co-express pluripotency-related proteins, such as SALL4, LIN28A, and LIN28B." (PMID 29802314, 2018). "We have previously shown that SALL4 (sal-like protein 4) is a critical transcription factor that regulates the stemness of gastric cancer cells." (PMID 29416741, 2018). "DANCR is activated by SALL4 in gastric cancer cells and exerted its oncogenic activities through the activation of β-catenin pathway." (PMID 29416741, 2018). "CD44 overexpression antagonized SALL4 knock-down-mediated inhibition of gastric cancer cell proliferation, migration, and invasion in vitro and gastric cancer growth in vivo." (PMID 29747682, 2018). "SALL4 was aberrantly elevated in multiple carcinomas, such as leukemia, germ cell tumors, liver cancer and gastric cancer, acting as an oncogene and biomarker." (PMID 28887597, 2017). "Over-expression of SALL4 enhanced gastric cancer cell proliferation and migration, whereas knocking down SALL4 reversed these effects." (PMID 28887597, 2017). "SALL4 was a potent stimulator for the expansion of human hematopoietic stem/progenitor cells, esophageal squamous cell and gastric cancers." (PMID 28887597, 2017). "Taken together, these results suggest that SALL4 regulates the expression of CD44 in gastric cancer cells through binding to its promoter." (PMID 27819668, 2016).
gastric cancer (continued). "Taken together, these results suggest that inducible knockdown of SALL4 also inhibits the proliferation and migration of gastric cancer cells." (PMID 27819668, 2016). "In conclusion, our findings suggest that CD44 is a downstream target gene of SALL4 and is partially responsible for the oncogenic roles of SALL4 in gastric cancer." (PMID 27819668, 2016). "Taken together, these results indicate that stable knockdown of SALL4 by shRNA inhibits the proliferation, migration and invasion of gastric cancer cells." (PMID 27819668, 2016). "We found that SALL4 knockdown induced apoptosis and cell cycle arrest at G1 phase in gastric cancer cells." (PMID 27819668, 2016). "To further confirm the biological roles of SALL4 on gastric cancer cell proliferation, migration and invasion, we established an inducible SALL4-targeting shRNA-expressing gastric cancer cell line by using the Tet-on system." (PMID 27819668, 2016). "We further confirmed the inhibitory effects of SALL4 knockdown on gastric cancer cells by using a tetracycline-inducible system." (PMID 27819668, 2016). "In the presence of tetracycline (Tet), SALL4 gene and protein expression decreased in gastric cancer cells as shown by the results of quantitative RT-PCR and western blot." (PMID 27819668, 2016). "We provided evidence that stable and inducible knockdown of SALL4 greatly reduced the proliferation, migration and invasion of gastric cancer cells and downregulated the expression of EMT and stemness-related genes." (PMID 27819668, 2016). "In this study, we observed the downregulation of CD44 in stable and inducible SALL4 knockdown gastric cancer cells." (PMID 27819668, 2016). "To demonstrate the biological roles of SALL4 in gastric cancer, we suppressed SALL4 expression in gastric cancer cells by using two short hairpin RNAs (shRNAs) that specifically target SALL4." (PMID 27819668, 2016). "Stable or inducible knockdown of SALL4 suppressed gastric cancer cell proliferation, migration and invasion, while CD44 overexpression antagonized these inhibitory effects." (PMID 27819668, 2016). "We next determined the effects of inducible SALL4 knockdown on gastric cancer cell proliferation, motility and migration." (PMID 27819668, 2016). "In this study, we demonstrated that SALL4 knockdown by short hairpin RNA greatly inhibited the proliferation, migration and invasion of gastric cancer cells." (PMID 27819668, 2016). "Since CD44 showed a decreased expression in SALL4 knockdown gastric cancer cells, we then focused on the regulatory role of SALL4 in CD44 expression." (PMID 27819668, 2016). "In this study we demonstrated that SALL4, a stem cell factor, promoted gastric cancer progression by activating CD44 expression." (PMID 27819668, 2016). "We then performed a chromatin immunoprecipitation assay to test the binding of SALL4 protein to CD44 promoter in gastric cancer cells." (PMID 27819668, 2016). "We next performed the rescue study to determine the importance of CD44 regulation to the oncogenic roles of SALL4 in gastric cancer." (PMID 27819668, 2016). "Taken together, these results indicate that CD44 overexpression antagonizes SALL4 knockdown-mediated inhibition of the proliferation, migration and invasion of gastric cancer cells in vitro." (PMID 27819668, 2016). "To characterize the role of IL-17B/IL-17RB signaling on the stemness of gastric cancer, we performed real-time quantitative PCR to examine the expression of Oct4, Nanog, Lgr5, and Sall4 mRNA in MGC-803 cells treated with exogenous rIL-17B." (PMID 27146881, 2016). "The results of cell counting assay showed that SALL4 knockdown decreased the growth of gastric cancer cells while CD44 overexpression significantly increased the growth of gastric cancer cells." (PMID 27819668, 2016).